RRP15 (ribosomal RNA processing 15 homolog)
Synonyms: KIAA0507; CGI-115
Tractability: Small molecule: a structure with a bound ligand is known. PROTAC: UniProt records ubiquitination sites on it; ubiquitination databases record sites on it; its protein half-life has been measured.
Gene: Protein-coding gene on chromosome 1 (218,285,290 to 218,337,983, forward strand). Ensembl gene ENSG00000067533.
Subcellular location (Human Protein Atlas): Mitotic chromosome; Nucleoli rim; Mitochondria; Nucleoplasm
Gene Ontology:
Biological process: maturation of 5.8S rRNA; maturation of LSU-rRNA; rRNA processing
Cellular component: preribosome, large subunit precursor
Genetic constraint (gnomAD): Loss-of-function variants: 13 observed, 21.75 expected, observed/expected ratio (o/e) 0.6, 90% interval 0.39 to 0.95. The upper end of that interval is the gene's LOEUF score, 0.95, which puts it in group 4 of 6, group 1 being the genes least tolerant of losing a copy. Missense variants: 329 observed, 325.7 expected, observed/expected ratio (o/e) 1.01, 90% interval 0.92 to 1.11. Synonymous variants: 104 observed, 109.53 expected, observed/expected ratio (o/e) 0.95, 90% interval 0.81 to 1.12.
Homologues: Orthologues: chimpanzee RRP15 (99% identical), macaque RRP15 (97% identical), rabbit RRP15 (80% identical), dog RRP15 (77% identical), mouse Rrp15 (73% identical), rat Rrp15 (73% identical), guinea pig RRP15 (72% identical), pig RRP15 (68% identical), tropical clawed frog rrp15 (50% identical), zebrafish rrp15 (46% identical), Drosophila melanogaster CG3817 (27% identical).
Diseases named in the same sentence as RRP15 in open-access papers:
RRP15 is named in the same sentence as 14 diseases in open-access papers, as found by Europe PMC text mining. Sharing a sentence is not in itself a finding about the gene and the disease. The quoted sentences say what the papers report.
breast carcinoma (3 papers, 2016 to 2023). "Another study showed that RRP15 depletion inhibited cell proliferation and delayed cell-cycle progression in HeLa cervical cancer or MCF7 breast cancer cells." (PMID 36834940, 2023).
Colon Cancer (2 papers, 2023 to 2024). "Although ribosomal RNA processing 15 Homolog (RRP15) has been implicated in the occurrence of various cancers and is considered a potential target for cancer treatment, its significance in colon cancer (CC) is unclear." (PMID 36834940, 2023). "In addition, another study demonstrated that elevated expression levels of RRP15 in colon cancer patient samples in comparison to normal tissue and exhibited poorer overall survival and disease-free survival in these patients." (PMID 38167959, 2024).
colorectal cancer (2 papers, 2023 to 2024). A primary or metastatic malignant neoplasm that affects the colon or rectum. "Deficiency of RRP15 decreased the proliferation and metastasis of colorectal cancer cells." (PMID 38475740, 2024).
hepatocellular carcinoma (2 papers, 2023). A malignant tumor that arises from hepatocytes.
liver cancer (2 papers, 2022 to 2023). An epithelial or non-epithelial malignant neoplasm that arises from the liver. "Thus, our study further expanded the scope of how RRP15 is involved in cancer development except for cervical, breast and liver cancer." (PMID 36834940, 2023).
melanoma (2 papers, 2019 to 2023). A malignant, usually aggressive tumor composed of atypical, neoplastic melanocytes. "This suggests that RRP15 mediated the development of UVR-induced melanoma." (PMID 36834940, 2023). "Notably, RRP15 was also involved in the occurrence and development of UVR-induced melanoma." (PMID 36834940, 2023). "Since Rrp15 is expressed virtually ubiquitously in the skin we do not know whether its mode of action in accelerating UVR-induced melanoma would be cell intrinsic or extrinsic." (PMID 30681412, 2019).
alcoholic steatohepatitis (1 paper, 2024). "In addition, we determined RRP15 expression from TCGA data based on the four major HCC etiologies, including HBV, HCV, alcoholic steatohepatitis, and non-alcoholic steatohepatitis." (PMID 38475740, 2024).
pancreatic cancer (1 paper, 2023). "Interestingly, one recent study reported a decreased expression in pancreatic cancer and that RRP15 was associated with cinchonine-induced cell death, while RRP15 knockdown could suppress autophagy and induce apoptosis." (PMID 36834940, 2023).
cancer (6 papers, 2017 to 2024). A tumor composed of atypical neoplastic, often pleomorphic cells that invade other tissues. "RRP15 is a critical nucleolar protein for RiBi and checkpoint control factor, and an RRP15 deficiency induces ribosomal stress through inhibition of the Wnt/beta-catenin pathway to suppress cell proliferation and metastasis, suggesting potential novel targets in patients with high-RiBi cancer." (PMID 38002277, 2023). "The focal adhesion pathway consists of multiple genes involved in cell motility and cancer metastasis, suggesting that RRP15 knockdown regulates the migration and invasion of HCC cells." (PMID 38475740, 2024). "RRP15 protein expression examined by IHC was significantly upregulated in cancer tissues as compared with surrounding normal tissues (P < 0.001), with 234 cases showing upregulation of RRP15 in cancer tissue." (PMID 36750557, 2023). "Proportional transcript abundance increased in two copies of the ribosomal RNA processing protein (RRP15) at high pH, which has been found to activate the G1/S checkpoint in cancer cells and thus inducing cellular arrest in G1 stage of interphase." (PMID 36504786, 2022). "Knocking down RRP15 in cancer cells resulted in cell cycle arrest or apoptosis." (PMID 38475740, 2024). "Interestingly, the correlation between RRP15 aberrant expression and carcinogenesis has been demonstrated in several cancers." (PMID 36834940, 2023). "Recent studies suggested that RRP15 could be a promising therapeutical target for cancer treatment; however, the potential molecular mechanism and clinical significance of RRP15 remains to be determined in CC." (PMID 36834940, 2023). "Ribosomal RNA processing 15 homolog (RPL15) promotes metastatic growth in multiple cancer organs, and enhancing the altered expression of RPL15 may alter the translational efficiency of ribosomes." (PMID 38002277, 2023). "Collectively, these results indicate that RRP15 expression in CRC cells is closely correlated with cell proliferation and cell cycle progression, and RRP15 may be a potential target to induce cancer-specific apoptosis in CRC cells." (PMID 36750557, 2023). "Our previous study revealed that RRP15 depletion specifically induced apoptosis in cancer cells (HeLa and MCF7) but not in an immortalized diploid cell line (hTERT-RPE1)." (PMID 36750557, 2023). "In summary, we investigated ribosomal RNA processing protein RRP15 involved in regulating nucleolar formation, ribosome biogenesis, cell proliferation, cell cycle progression and checkpoint control in human non-transformed and cancer cells." (PMID 28099941, 2017). "In this study, we investigated ribosomal RNA processing protein RRP15 involved in regulating nucleolar formation, ribosome biogenesis, cell proliferation, cell cycle progression and checkpoint control in human non-transformed and cancer cells." (PMID 28099941, 2017).
tumor (4 papers, 2017 to 2024). "Reversely, β-catenin expression was significantly elevated in xenograft tumor tissues when RRP15 OE, and displayed positively associated with RRP15 expression (R = 0.5086, P = 0.0156)." (PMID 36750557, 2023). "Consistent with this, RRP15 depletion also decreased the tumor weight and overall tumor size compared to that in the control group." (PMID 38475740, 2024). "The results showed that RRP15 KD significantly retarded the tumor growth, whereas ectopic RRP15 obviously accelerated the tumor growth." (PMID 36750557, 2023). "Results of IHC staining showed that the expression of β-catenin in xenograft tumor tissues was diminished when RRP15 KD, and a positive correlation between β-catenin and RRP15 expression was observed (R = 0.361, P = 0.0331)." (PMID 36750557, 2023). "In contrast, overexpression of RRP15 promoted CC cell proliferation, colony formation and invasion in vitro, and enhanced tumor growth in vivo." (PMID 36834940, 2023). "We demonstrate that RRP15 is upregulated in CRC cell lines along with tumor tissues, and can be used to predict the prognosis of CRC patients." (PMID 36750557, 2023). "We further examined the relationship between RRP15 and β-catenin in xenograft and pathological tumor tissues." (PMID 36750557, 2023). "Consistent with TCGA data, the expression of RRP15 mRNA is frequently increased in tumor tissues as compared with the corresponding paracarcinoma tissues from 20 CRC patients." (PMID 36750557, 2023). "We also observed that RRP15 knockdown suppressed the proliferation, colony formation and invasion, and notably suppressed tumor growth." (PMID 36834940, 2023). "CC xenografts nude mice model were examined to study the effects of RRP15 overexpression or knockdown on tumor growth in vivo." (PMID 36834940, 2023). "Additionally, in a nude mouse HCC xenograft model established using MHCC-97H cells, the tumor volume of RRP15 knockout nude mice was significantly reduced 15 days after inoculation compared to controls." (PMID 38475740, 2024). "Transwell assays revealed that RRP15 knockdown notably reduced cell invasion, whereas its overexpression markedly increased cell invasion, indicating that inhibition of RRP15 suppressed the tumor invasion of CC cells." (PMID 36834940, 2023). "Therefore, we provide evidence showing that RRP15 knockdown suppressed tumor growth, invasion and the EMT of CC." (PMID 36834940, 2023). "Furthermore, depletion of RRP15 inhibited the tumor growth, induced DNA damage and apoptosis, induced glucose metabolism remodeling and cellular senescence in HCC." (PMID 36834940, 2023). "Collectively, inhibition of RRP15 suppressed tumor growth, invasion and EMT of CC, and might be considered a promising therapeutic target for treating CC." (PMID 36834940, 2023). "In contrast, the knockdown of RRP15 decreased the tumor weight and volume of HCT15 CC xenografts, suggesting that RRP15 knockdown could inhibit CC cell growth in vivo." (PMID 36834940, 2023). "The expression of RRP15 in HCC tissue microarray (TMA), tumor tissues and cell lines were determined." (PMID 38475740, 2024). "We found that RRP15 overexpression enhanced HCT116 CC xenografts’ growth, tumor weight and volume compared to the control group." (PMID 36834940, 2023).
RRP15 also shares sentences with these, for which no sentence is quoted: cervical cancer (1 paper); non-alcoholic steatohepatitis (1); renal cell carcinoma (1); triple-negative breast carcinoma (1).